ROR1 (ROR family WNT receptor 1)
Diseases named in the same sentence as ROR1 in open-access papers (continued):
Sharing a sentence is not in itself a finding about the gene and the disease.
tumor (continued). "ROR1, virtually absent in normal adult tissues, exhibits activity in various malignancies and has been linked to tumor cell growth." (PMID 38558536, 2024). "Evidence for the involvement of ROR1 in malignancies is based on its expression on tumor cells." (PMID 39551787, 2024). "These CAR-T cells target different antigens, but ROR1 was the tumor antigen selected in just five studies, namely, two for hematological malignancies (NCT02194374 and NCT05588440), two for solid tumors (NCT05274451 and NCT05638828), and one for both (NCT02706392)." (PMID 36873868, 2023). "Noteworthy, we identified ROR1 and pSTAT3 staining in the same tumor cells, which indicates that these proteins are co-expressed and could modulate OC tumor heterogeneity." (PMID 37400436, 2023). "Our data sets the stage to further validate compound 4 as a ROR1-inhibitor and an anti-tumor agent." (PMID 37779899, 2023). "In addition, reduced tumor growth was observed in ROR1-siRNA-FENPs-treated mice, along with enhanced necrosis as compared to controls." (PMID 37190185, 2023). "For this purpose, R11 ROR1-CAR-T cells were further transfected to express a synNotch receptor directed against a different tumor antigen (epithelial cell adhesion molecule (EpCAM) or B7-H3) expressed exclusively on ROR1+ tumor cells." (PMID 36873868, 2023). "ROR1 is involved in a lot of functions in tumor cells, such as proliferation, survival, migration, stemness, epithelial to mesenchymal transition (EMT), chemotaxis, and drug resistance, through the planar cell polarity (PCP) activation and Ca2+ dependent pathways of non-canonical Wnt signaling." (PMID 37111634, 2023). "They then evaluated the effector activity of these ROR1 CAR-T cells against ROR1+ tumor cells." (PMID 36873868, 2023). "Since we identified STAT3 as a downstream transcription factor modulated by ROR1 expression, we also investigated whether ROR1+ tumor cells are pSTAT3+ (Y705)." (PMID 37400436, 2023). "Conventional receptor tyrosine kinase-like orphan receptor 1 (ROR1)-targeted CAR-T cells not only lyse ROR1+ tumor cells but also attack ROR1+ normal stromal cells, which may cause therapeutic iatrogenic toxicity." (PMID 37131214, 2023). "Moreover, after 5 days of in vitro rechallenge with ROR1+ tumor cell lines, all T cells transduced with the 3G-constructs secreted significantly higher IFN-γ levels than the 2G-CAR construct and UTD control." (PMID 37719008, 2023). "Thus, our analyses demonstrate that tumor EVs carrying either ROR1 or ROR2 support an aggressive phenotype in cancer cells even after efficiently inhibiting their uptake into target cells." (PMID 37430307, 2023). "In cancer, ROR1 is highly dysregulated and plays a key role in tumor progression." (PMID 38213538, 2023). "Jeko-1 tumor-bearing mice showed a significant response after injection of ROR1-IOζ CAR T-cells." (PMID 37719008, 2023). "Since our results had revealed that ROR1/2 can be spread via EVs to surrounding cells, we tested whether the presence of ROR1 affects the biodistribution of tumor EVs in the 4T1 mouse model." (PMID 37430307, 2023). "Finally, the feasibility of applying the ROR1 CAR-T cell strategy in combination with therapies targeting other tumor antigens or with inhibitors that prevent tumor antigenic escape is also discussed." (PMID 36873868, 2023). "Moreover, immunotherapy with autologous T-cells engineered to express a ROR1-specific chimeric antigen receptor (ROR1 CAR-T cells) has emerged as a personalized therapeutic option for patients with tumor recurrence after conventional treatments." (PMID 36873868, 2023). "Interestingly, circulating tumor cells (CTCs) from patients with pancreatic cancer (PAC) showed higher levels of ROR1 and greater proliferative and invasive potential compared to cells from non-cancerous tissues and the PAC cell lines, PANC-1 and SW-1990." (PMID 36873868, 2023).
tumor (continued). "However, this elevated “baseline” TCM predominance changed after the cells were evaluated using our five days in vitro rechallenge assay with ROR1+ tumor cell lines." (PMID 37719008, 2023). "Potential limitations of our study include the analysis of pretreatment tumor specimens only, analysis of gene expression only, and use of Agilent 44 K platform which cannot distinguish between RNA isoforms of ROR1 or ROR2 that can or cannot be expressed as cell surface proteins." (PMID 37029329, 2023). "The oncogenic functions of these receptors can be unleashed through amplification and overexpression via transcriptionally regulated mechanisms, and elevated ROR1, ROR2, and PTK7 expression is linked to tumor development and metastasis in several hematological as well as solid malignancies." (PMID 35504983, 2022). "Moreover, we compared ROR1-specific immune responses and tumor growth inhibition induced by H17 fusion protein in combination with two different adjuvants, including Freund’s and CpG." (PMID 36497309, 2022). "In addition, the anti-tumor function of the ROR1-CAR T cells can be enhanced with SD-208, a highly selective, competitive, and orally bioavailable TGF-β-receptor I kinase inhibitor in a microphysiologic 3D TNBC model." (PMID 35795050, 2022). "ROR1 is an important molecule for the malignant phenotype, e.g., tumor cell proliferation, survival, epithelial–mesenchymal transition (EMT), migration, and metastasis, and been suggested to be an interesting target molecule for precision cancer medicine (PCM)." (PMID 36297673, 2022). "Similar to non-diseased tissues, ROR1-v3 rather than ROR1-v1 was the most highly expressed transcript variant in all tumour types analysed." (PMID 36289823, 2022). "Finally, results of tumor challenge in immunized mice showed that immunization with TT-mROR1-Fc fusion proteins completely inhibited ROR1+ tumor cells growth in two different syngeneic tumor models until day 120 post tumor challenge." (PMID 36497309, 2022). "However, variability in expression of both proteins is seen on the tumor cells, with more variable expression of ROR1 than CD19." (PMID 36922932, 2022). "ROR1 is an oncogenic RTK involved in the survival of tumor cells of various origins." (PMID 36297673, 2022). "ROR1-CAR T-cells are cytotoxic specific to ROR1-expressed tumor cells." (PMID 36557069, 2022). "In this study, to break immunologic tolerance to a self TAA (mROR1 protein), we designed and produced five different recombinant fusion proteins of mROR1 and investigated their immunogenicity and protective efficacy as an anti-cancer candidate vaccine in fully syngeneic ROR1+ mouse tumor models." (PMID 36497309, 2022). "A ROR1-CAR T cells have the anti-tumor function on TNBC cell line MDA-MB-231." (PMID 35795050, 2022). "Despite many interests in use of ROR1 molecule as a target for cancer active therapy, so far it has not been introduced in syngeneic ROR1+ animal model and several studies have commonly used human tumor xenografts model in immunosuppressive microenvironments." (PMID 36497309, 2022). "While the efficacy of CAR-T in solid tumor remained a challenge, our ROR1 Hinge CAR-T-cells significantly suppressed tumor growth compared to the control groups in different solid tumor xenograft models, suggesting the ROR1 Hinge CAR is also effective against different types of solid tumors." (PMID 35892876, 2022). "We assessed the 4-1BB expression on ROR1 Hinge CAR-T after incubating with different tumor cells." (PMID 35892876, 2022). "Because of the toxicity of ROR1-targeted CAR-T cells attributable to ROR1 expression in normal tissues, CAR-T cells have been engineered with synthetic Notch receptors EpCAM and B7-H3 to improve selectivity, specificity, and tumor regression in ROR1-expressing tumor cells with less toxicity." (PMID 35720364, 2022). "Hence, another approach is to develop syngeneic mouse ROR1+ tumor models and assess the anti-tumor effects of active immunization in mice." (PMID 36497309, 2022).
tumor (continued). "We further evaluated the anti-tumor effect of ROR1 Hinge CAR-T against other solid tumor models." (PMID 35892876, 2022). "The receptor-like tyrosine kinase-like orphan receptor 1 (ROR1) is an embryonic protein that plays an important role in cell proliferation, differentiation, and angiogenesis, but is also overexpressed in cancer and induces tumor migration and metastasis." (PMID 36428576, 2022). "Importantly, arterial tissues expressed the highest levels of ROR1 mRNA, highlighting a need to monitor the on-target off-tumour effects of ROR1 therapy on the circulatory system." (PMID 36289823, 2022). "Oxaliplatin and anti-PD-L1 synergistically improved ROR1-targeted CAR-T cell anti-tumor ability." (PMID 35935930, 2022). "Our results showed that a fusion protein containing mouse ROR1, IgG Fc, and a universal tetanus toxin (TT) helper T-cell carrier could break tolerance against mouse ROR1 autoantigen and completely inhibit the growth of syngeneic ROR1+ tumor cells." (PMID 36497309, 2022). "While most samples had ROR1+ cells, this population was entirely restricted to the PB tumor cells." (PMID 36922932, 2022). "Overall, the cohort showed a broad range of expression levels for ROR1 in PDAC tumour tissues." (PMID 34763666, 2021). "Furthermore, ROR1 was positively correlated with regulatory T cells and M2-type macrophages and negatively correlated with Th17 and natural killer T cells in the tumor stroma of patients with GC." (PMID 34319035, 2021). "Tumor-derived exosomal circRNA_102481 could contribute to EGFR-TKIs resistance in NSCLC by sponging miR-30a-5p to enhance ROR1 expression." (PMID 33952725, 2021). "ROR1 (receptor tyrosine kinase-like orphan receptor 1) is an oncofetal tyrosine kinase involved in the progression of intrauterine development, which expresses highly in several neoplasms." (PMID 34421987, 2021). "Taken together, this raises the question whether ROR1 solely functions as a bystander molecule upregulated during tumor progression, or whether the functional consequence of WNT/ROR signaling is highly context-specific as discussed later in this article." (PMID 33445713, 2021). "In addition, the inhibition of TGF-β-receptor signaling augments the anti-tumor function of ROR1 (receptor-tyrosine-kinase-like orphan receptor 1)-specific CAR T-cells against TNBC." (PMID 35111680, 2021). "It is also possible to target molecules expressed on tumor cells but absent or lowly expressed on healthy cells, such as ROR1 or GD2, or neoantigens present due to oncogenic mutation." (PMID 33670942, 2021). "It was observed that in positive samples all tumor cells stained for ROR1 and BCL2 expression." (PMID 34088900, 2021). "ROR1, in turn, supported tumor colonization and metastasis formation at these sites." (PMID 33445713, 2021). "Furthermore, the immunonanoparticle-mediated ROR1-targeted delivery of OSU-2S, a sphingosine analogue with anti-tumor activity, showed promising potency in ROR1-positive malignant cells in preclinical studies." (PMID 34123850, 2021). "Previously, we could demonstrate that human CD8+ T lymphocytes equipped with a ROR1-CAR exert specific anti-tumor reactivity in vitro and xenograft models in immunodeficient mice." (PMID 34210970, 2021). "Compared to the tumour tissue, normal samples showed lower expression of ROR1 or ROR2." (PMID 32807831, 2020). "Thus, CAR T-cells exhibited selective cytotoxicity to ROR1+ tumor cells, while avoiding ROR1+ stromal cells." (PMID 33348704, 2020). "Targeting ROR1 may reduce ‘on-target, off-tumour’ toxicities compared to CARs targeting CD19/20/22, however, it has been found that ROR1 is expressed on pancreatic and lung tissue suggesting potential for other toxicities." (PMID 32645977, 2020).
tumor (continued). "A higher apoptotic rate of DLBCL cells in the absence of stromal cells was noted as compared to when stromal cells were present, indicating that the ROR1 inhibitor could only partially overcome the tumor-promoting effects of stromal cells in this system." (PMID 32586008, 2020). "WNT5A has dual effects on the tumor microenvironment; it can promote inflammation and chemotaxis of immune cells through activation of the ROR1/Akt/P65 pathway, as well as stimulating the TLR/MyD88/p50 pathway in myelomonocytic cells, to promote synthesis of the anti-inflammatory cytokine, IL-10." (PMID 33034614, 2020). "In general, ROR1 promoted tumour growth and progression in EC cell lines in vitro." (PMID 32807831, 2020). "Targeting ROR1 with small molecules or immunological procedures may increase the sensitizing of tumor cells, particularly erlotinib-resistant cells, to erlotinib." (PMID 31452776, 2019). "Additionally, our group is developing anti-ROR1 CAR engineered expanded primary NK cells through CAR mRNA electroporation technology to target ROR1+ solid tumors with promising in vitro anti-tumor effects." (PMID 30805309, 2019). "In light of these, we hypothesized that huNSG mice have a high proportion of ROR1+ B cells and could represent a ROR1+ tumor model in vivo." (PMID 29850623, 2018). "However, it should be noted that on-target/off-tumor toxicity must be taken into consideration when using anti-ROR1 CAR-T because of its expression on other normal tissues, such as parathyroid, pancreatic islet cells, and gastrointestinal tract." (PMID 30458878, 2018). "Interfering with the ROR1 signaling pathway might be a successful approach to induce tumor cell apoptosis." (PMID 29725030, 2018). "ROR1 is of importance for e.g., tumor cell proliferation, survival, and metastasis." (PMID 29725030, 2018). "Preclinical data demonstrated that CAR-T cells can accurately recognize autologous ROR1-expressing tumor cells or cell lines and could serve as a powerful weapon to eliminate chemotherapy resistant CLL cells." (PMID 30458878, 2018). "However, our ROR1 BiTE was able to mediate efficient and equivalent killing of tumor cells with low and high levels of ROR1 with relatively low effector to target ratio." (PMID 28811962, 2017). "Ror1 could enhance the survival of tumor cells by either kinase-dependent or kinase-independent pathways." (PMID 28432357, 2017). "Furthermore, tumor-cell expression of ROR1 apparently correlates with the expression of ALDH1 and the capacity to form tumor spheroids in vitro (both markers of CSC)." (PMID 28491097, 2017). "Moreover, it was shown that down-regulation of Ror1 suppressed the expression of EMTrelated genes and the migratory and invasive abilities of the tumour." (PMID 28432357, 2017). "Further data showed the c-Src/STAT3 signaling pathway may be involved in miR-27b-3p-ROR1-mediated tumor cell proliferation." (PMID 29212222, 2017). "Moreover, our results showed that higher score of ROR1 was positively correlated to advanced tumor stage and positive lymph node metastasis in CRC patients." (PMID 28427197, 2017). "Furthermore, a direct correlation was observed between ALDH1, a marker of ovarian CSCs, formation of tumor spheroids in vitro, and Ror1 expression." (PMID 27571105, 2016). "Because of its tumor-specific expression and absence on normal mature cells, ROR1 could be a potential candidate for CAR (Chimeric antigen receptor) -T cell therapy." (PMID 27830754, 2016). "In summary, we investigated the clinicopathological relevance of ROR1 expression in a large cohort of lung ADC patients for the first time, and found that ROR1 is specifically expressed at higher levels in lung ADC tissue than that in adjacent non-tumor tissue." (PMID 27830754, 2016). "A ROR1 specific spontaneous immune response may support the assumption of ROR1 as a tumor neo-antigen." (PMID 26562161, 2015).
tumor (continued). "Thus, adoptive transfer of T cells specific for ROR1 has potential to eliminate tumor cells and spare healthy tissues." (PMID 26030772, 2015). "ROR1 may serve as a potential target for cancer therapy, and a tumor promoter in a variety solid malignancies, such as breast, lung, ovarian neoplasms." (PMID 26576539, 2015). "The ROR1 is shown to play a role in tumor-like behavior, such as cell migration and cell invasiveness and are negatively expressed in normal adult tissue, ROR1 has recently been found to be expressed in human cancers, and have the potential to be cancer targets." (PMID 26576539, 2015). "Thus, this staining dataset corroborated our rationale to use the 4A5 mAb to construct CARs specific for ROR1 expressed on tumor cells." (PMID 26030772, 2015). "Tumors from cells silenced for ROR1 had lower ROR1 expression, 5 times more apoptotic cells, and significantly lower proportions of cells that stained for the proliferation marker Ki-67 than did tumors derived from control-treated tumor cells." (PMID 22403610, 2012). "Because of the selective expression of ROR1 by neoplastic cells and its apparent role in promoting tumor-cell growth, ROR1 may serve as a potential target for development of anti-cancer therapies." (PMID 22403610, 2012). "Thus, although ROR1 targeting may alleviate off-tumor toxicity, long-term administration of the degrader should be avoided." (PMID 39816690, 2025). "In addition, the development of a new v1-specific anti-ROR1 Ab for IHC should reduce the amount of ROR1 tumour staining, which may impact it prevalence in MCL, DLBCL and FL by reducing the values shown at this point." (PMID 39495778, 2024). "Overall, ROR1 expression was relatively infrequent and low in most tumor types investigated; however, ROR1 expression was infrequent but high in selected tumor types, such as gastroesophageal GIST, suggesting that ROR1 prescreening may be preferable for those indications." (PMID 38791952, 2024). "In contrast, PD-PDX kinases with potential to be restored by the addition of MSCs include ACVR1C (ALK7), MAP3K14 and ROR1, which may be inhibitors of tumour growth, and JAK1, involved in the STAT3 signalling pathway characteristic of the inflammatory molecular subclass of CCA." (PMID 39492622, 2024). "Therefore, some transformation must occur during tumor growth and expansion, suggesting that ROR1 positive exosomes in PF might play an important role in the development of peritoneal carcinomatosis in PDAC patients." (PMID 38846943, 2024). "However, some advances in the treatment of solid tumors are currently employing the ROR1 antigen as a critical target due to its high expression in tumor cells and relatively scarcity in normal tissues, as well as its presence in CSCs responsible for relapses and treatment resistance." (PMID 36873868, 2023). "In addition, some strategies developed for other tumor therapeutic targets could help improve the functionality of different ROR1 CAR-T cells and, consequently, the clinical outcomes of this cancer immunotherapy." (PMID 36873868, 2023). "Tumor-derived exosomal circRNA_102481 may promote resistance to epidermal growth factor receptor tyrosine kinase inhibitors (EGFR-TKIs) in NSCLC via the miRNA-30a-5p/ROR1 axis." (PMID 35382838, 2022). "Furthermore, surprisingly ROR1-v3 appears to be the predominantly expressed variant in both non-diseased and tumour tissues." (PMID 36289823, 2022). "However, the expression level of ROR1 on the aAPCs is higher than on the CLL tumor." (PMID 36922932, 2022). "However, as an oncoprotein, ROR1 can reemerge in hematological and solid tumors, especially in histologically advanced tumors, where ROR1 may promote tumor cell migration through Wnt5a signaling or interaction with other receptors." (PMID 35480093, 2022). "Therefore, it was concluded that tumor-derived exosomal circRNA_ 102481 could contribute to EGFR-TKIs resistance via the microRNA-30a-5p/ROR1 axis in NSCLC." (PMID 33952725, 2021).